YAP1 (Yes1 associated transcriptional regulator)
Diseases named in the same sentence as YAP1 in open-access papers (continued):
Sharing a sentence is not in itself a finding about the gene and the disease.
melanoma (61 papers, 2014 to 2025). A malignant, usually aggressive tumor composed of atypical, neoplastic melanocytes. "The lncRNA-ATB–miR-590-5p–Yes1-associated transcriptional regulator (YAP1) also stimulates the migration and invasion of melanoma cells." (PMID 41463281, 2025). "To evaluate the mechanism that controls CAF phenotypes by YAP1 signaling, we established inducible YAP1-deficient CAFs using shRNA in different human melanoma-derived CAF cell lines, including M27 and M50." (PMID 38308096, 2024). "In the present study, analysis of data downloaded from TCGA database revealed that YAP1 was positively associated with genes related to copper-induced cell death in patients with melanoma." (PMID 38515849, 2024). "Here, we report a novel mechanism underlying cadherin switching in melanoma cells that is regulated by stromal Yes-associated protein 1 (YAP1) signaling." (PMID 38308096, 2024). "The progression of a BRAF-mutant mouse melanoma was suppressed in vivo upon YAP1 ablation in cancer-associated fibroblasts (CAFs)." (PMID 38308096, 2024). "D4M melanomas carrying YAP1-deficient CAFs (named YAP1 KO) grew slower than tumors carrying CAFs expressing normal levels of YAP1 (named Ct)." (PMID 38308096, 2024). "In this study, two mouse models carrying either YAP1-deficient CAFs or YAP1-overexpressing CAFs showed opposite effects on in vivo melanoma growth, reflecting the importance of YAP1 in CAFs and of CAFs for melanoma development." (PMID 38308096, 2024). "As expected, the number of melanoma cells (α-SMA-) that were Ki67+ was decreased in melanomas carrying YAP1-deficient CAFs." (PMID 38308096, 2024). "So, we examined the association between YAP1 expression and immune cell infiltration in patients with melanoma." (PMID 38515849, 2024). "The observation of a loose spheroid structure is consistent with what we observed in mouse melanoma carrying YAP1-deficient CAFs." (PMID 38308096, 2024). "In this study, we established two mouse models that carry either YAP1-deficient CAFs or YAP1-overexpressing CAFs and demonstrated that YAP1 is important for CAFs to promote in vivo melanoma progression." (PMID 38308096, 2024). "Compared to Class I enhancers, Class III enhancers are sparsely mutated by different forms among melanoma patients, while Class IV enhancers are highly duplicated across many oncogene loci (such as YAP1)." (PMID 37904237, 2023). "The SLC35B2 knockout-dependent loss of HS expression was associated with re-sensitization of YAP1-activated melanoma cells toward MAPKis in vitro and in vivo." (PMID 35798875, 2022). "Using a genome-wide screen in melanoma cells with defined levels of YAP1 activity, we identified vulnerabilities associated with YAP1/TAZ activity in general and specifically in the context of MAPKi treatment." (PMID 35798875, 2022). "For example, miR-590-5p suppressed cell proliferation and tumor growth in melanoma by regulating Yes-associated protein 1 (YAP1)." (PMID 32051829, 2020). "Moreover, studies observed co-heterozygous loss of LATS1/2 and amplification of YAP1 in primary and metastatic human melanoma." (PMID 38515849, 2024). "In addition, the suppressive phenotypes contributed by YAP1 deficiency in CAFs were faithfully replicated in human melanoma xenografts." (PMID 38308096, 2024). "Moreover, we overexpressed N-cadherin in YAP1-deficient CAFs and melanoma cells to understand if the phenotypes in melanoma cells caused by YAP1 deficiency in CAFs can be rescued by N-cadherin activity." (PMID 38308096, 2024). "Yes1-associated transcriptional regulator (YAP1) is highly expressed in melanoma and may be related to MEK inhibitor resistance." (PMID 38169595, 2024). "Another explanation could be that YAP1-deficient or N-cadherin-deficient CAFs are unable to produce cytokines or molecules that are necessary for the maintenance of N-cadherin expression and membrane presentation in melanoma cells." (PMID 38308096, 2024).
melanoma (continued). "Because nuclear translocation of YAP1 is modulated by the Wnt/β-Catenin pathway in melanoma-associated fibroblasts and YAP1 is necessary to transactivate FSTL3 gene expression, we hypothesized that elevated FSTL3 expression modulates β-Catenin signaling in CRC." (PMID 34395416, 2021). "Transcriptomic and biochemical analyses further revealed that CuPaeNs suppressed melanoma glycolysis by blocking the fascin-YAP1-PFKFB3 signaling axis." (PMID 41405370, 2025). "Overall, these data suggest a more substantial role for TAZ versus YAP1 in regulating the transcriptome in melanoma cells." (PMID 41193428, 2025). "LncRNA MSC-AS1 promotes glutaminolysis to enhance tumor proliferation by modulating miR-330-3p/YAP1 axis in melanoma." (PMID 41145465, 2025). "We examined the dependency on YAP1 and TAZ expression of canonical TEAD targets in SOX10-deficient melanoma by siRNA knockdown." (PMID 41193428, 2025). "Overall, these data show that despite no overt change in TAZ/TEAD expression, SOX10-low, drug-tolerant cells exhibit up-regulation of YAP1/TAZ-TEAD signaling in melanoma, likely through multiple mechanisms including chromatin remodeling and c-Jun upregulation." (PMID 41193428, 2025). "This pathway is frequently deregulated in melanoma, with YAP1, a hub node in the Hippo pathway, playing a crucial role in promoting cell proliferation and metastasis in melanoma." (PMID 40827204, 2025). "Nevertheless, further exploration of YAP1 and N-cadherin as therapeutic targets to inhibit melanoma metastasis and improve targeted therapies and immunotherapies is warranted." (PMID 38308096, 2024). "Consistent with the reduced YAP1 KO tumor size and weight, the number of melanoma cells (α-SMA-negative, α-SMA-) that were Ki67-positive (Ki67+) and the number of cyclin D1-positive (cyclin D1+) cells were both decreased in YAP1 KO melanomas." (PMID 38308096, 2024). "In summary, we identified a new vulnerability for MEK inhibitor-resistant melanomas, which have an activated Hippo pathway due to elevated YAP1 activity." (PMID 38169595, 2024). "The contents of collagen and fibronectin were also higher in YAP1 melanomas than those in control melanomas." (PMID 38308096, 2024). "Although most studies on the Hippo signaling pathway’s engagement in melanoma are focused on the YAP1 oncotarget, several pieces of evidence point to the high importance of its core kinases in regulating that cancer." (PMID 38920690, 2024). "In contrast, the expression of N-cadherin was increased in both CAFs and melanoma cells when YAP1 was overexpressed in CAFs." (PMID 38308096, 2024). "The number of α-SMA+ CAFs and contents of collagen and fibronectin were both significantly reduced in melanomas upon YAP1 ablation." (PMID 38308096, 2024). "Inhibition of BRD4 using BET inhibitors suppressed YAP1 expression and led to blunted melanoma growth when combined with treatment with the MEK inhibitor trametinib." (PMID 38169595, 2024). "To further investigate the role of YAP1 in melanoma progression, we analyzed YAP1 expression in the tumor stroma of patients who responded and nonresponded to trametinib treatment." (PMID 38169595, 2024). "Analysis of YAP1 expression in melanoma patients treated with trametinib showed that YAP1 expression was negatively correlated with the response and survival in these patients." (PMID 38169595, 2024). "Together, these data suggest that BET inhibitors suppress melanoma proliferation by downregulating YAP1 expression." (PMID 38169595, 2024). "The expression of N-cadherin was markedly reduced, especially in melanoma cells (α-SMA-), in melanoma containing YAP1-deficient CAFs." (PMID 38308096, 2024). "To assess the contribution of YAP1 signaling in CAFs to BRAF-mutant melanoma progression in vivo, we generated a transgenic mouse model, α-SMA-CreERT2; Yap1loxP/loxP, which allows the inducible ablation of YAP1 expression in CAFs." (PMID 38308096, 2024).
melanoma (continued). "YAP1 silencing reduced N-cadherin expression in CAFs, leading to the downregulation of N-cadherin in neighboring melanoma cells." (PMID 38308096, 2024). "In conclusion, the present study demonstrated the prognostic value of Hippo pathway-related genes (particularly YAP1) in melanoma, revealing the correlation between the expression of Hippo pathway-related genes and immune infiltration." (PMID 38515849, 2024). "Histological analysis showed that YAP1 melanomas had a more compact internal structure than control tumors." (PMID 38308096, 2024). "RNA-Seq revealed that the gene that stands out and is most downregulated in CAFs after YAP1 loss is N-cadherin, a molecule that spearheads CAF-melanoma interactions and tumor invasion after melanoma cells undergo the switch from E-cadherin to N-cadherin." (PMID 38308096, 2024). "The data clearly demonstrated that N-cadherin expression in melanoma cells is modulated by YAP1-regulated N-cadherin expression in CAFs." (PMID 38308096, 2024). "We also treated a panel of melanoma cells, including YUSOC, YUGASP, YUAME, YUMAC and SK-MEL-28 cells, with 10 nM NHWD-870 and found that YAP1 protein levels decreased in all these different melanoma cells." (PMID 38169595, 2024). "The data suggest that YAP1 activity is important for CAFs to support melanoma cell proliferation in vivo." (PMID 38308096, 2024). "Several studies have revealed that YAP1 plays a critical role in melanoma proliferation and metastasis 8, 9, suggesting that YAP1 is a potential therapeutic target." (PMID 38169595, 2024). "H&E staining revealed that the structure of YAP1 KO melanomas was less compact with more intercellular spaces than that of Ct tumors." (PMID 38308096, 2024). "Consistently, Kaplan‒Meier analysis showed that the change in nuclear YAP1 expression after trametinib treatment was significantly correlated with poor prognosis in these melanoma patients." (PMID 38169595, 2024). "The data further confirm that YAP1 indeed plays a crucial role in CAFs to support melanoma development." (PMID 38308096, 2024). "Immunohistochemistry of YAP1 with strong immunoreactivity of areas A and the flanking melanoma in situ visualizes these two heterogeneous subpopulations." (PMID 39034322, 2024). "In melanoma patient samples, YAP1 is reported to be highly expressed due to copy number alteration, and its expression is correlated with poor prognosis." (PMID 38169595, 2024). "The findings suggest that YAP1 depletion in CAFs induces the downregulation of p-AKT signaling in melanoma cells through the N-cadherin-mediated interaction between melanoma cells and CAFs." (PMID 38308096, 2024). "To further investigate the roles of BET inhibitors in melanoma, we performed RT‒qPCR and western blot analyses for YAP1 expression in A375 and SK-MEL-28 cells treated with different doses of NHWD-870 and JQ1." (PMID 38169595, 2024). "The number of α-SMA+ CAFs per mm2 was increased from 314 ± 35 in control melanomas to 450 ± 44 in YAP1 melanomas." (PMID 38308096, 2024). "On the other hand, we evaluated the transcriptomes of melanoma samples from patients before and after trametinib treatment and investigated the correlation between YAP1 expression and trametinib resistance." (PMID 38169595, 2024). "Taken together, our work uncovers a novel YAP1-regulated cellular mechanism that controls melanoma cell phenotypes and proliferation through the N-cadherin-mediated interaction between melanoma cells and CAFs." (PMID 38308096, 2024). "On day 21, when the tumors were collected, the average size and weight of YAP1 melanomas (1287.99 ± 286.13 mm3, 1.30 ± 0.23 g) exceeded those of control tumors carrying normal CAFs (829.98 ± 136.48 mm3, 0.96 ± 0.28 g)." (PMID 38308096, 2024). "In melanoma, YAP1 played an important role in activating Tregs, thus facilitating the generation of an immunosuppressive TME." (PMID 37752152, 2023).
melanoma (continued). "In NSCLC and melanoma, the expression level of PD-L1 was regulated by YAP1, while little was known about the role of YAP1 in SCLC." (PMID 37752152, 2023). "Here, we show that upon Yes-associated protein 1 (YAP1) ablation in cancer-associated fibroblasts (CAFs), the progression of a BRAF-mutant mouse melanoma was significantly suppressed in vivo, and overexpressing YAP1 in CAFs accelerated melanoma growth." (PMID 37546745, 2023). "YAP1 silencing led to N-cadherin downregulation in CAFs, which subsequently induced the downregulation of N-cadherin in neighboring melanoma cells." (PMID 37546745, 2023). "We observed an enrichment of NF-κB targets in YAP5SA cells compared to controls, suggesting YAP1 as a transcriptional activator of NF-κB signaling in melanoma cells." (PMID 35798875, 2022). "The only one YAP1 amplification acral melanoma case in our cohort showed diffuse plasma expression of YAP1 protein." (PMID 36428972, 2022). "In YAP1-activated melanoma cells, SLC35B2 knockout abrogated HS surface expression and limited activity of YAP1-stimulated RTKs including ERBB3, EGFR, and AXL." (PMID 35798875, 2022). "As the engineered YAP1-activated melanoma cell lines modeled a clinically relevant mode of drug resistance, we sought to systematically identify vulnerabilities in these cells using a genome-wide CRISPR/Cas9 screen." (PMID 35798875, 2022). "While sensitivity marker genes were suppressed in YAP5SA melanoma cells, resistance markers were upregulated, supporting the role of YAP1 as a molecular driver of the MITFlow/AXLhigh-resistance phenotype in melanoma." (PMID 35798875, 2022). "The phenotypic shift induced in melanoma cells by these double treatments is dependent on YAP1 (yes-associated protein 1)- and MRTFA (Myocardin Related Transcription Factor A)-activity in resistant melanoma cells." (PMID 35558554, 2022). "This supports the dependency of MAPKi resistance on active ERBB signaling in MITFlow/AXLhigh melanoma cells with high YAP1/TAZ activity." (PMID 35798875, 2022). "Here, we show particularly high YAP1/TAZ activity in MITFlow/AXLhigh melanomas characterized by resistance to MAPK pathway inhibition and broad receptor tyrosine kinase activity." (PMID 35798875, 2022). "Although the effect of YAP1 on invasion is clearly documented, its effect on melanoma growth is still debated." (PMID 35158973, 2022). "Genetic inhibition of TEAD1-4 recapitulates the in vitro effects of YAP1 on invasion, with a clear decrease in the invasive capacity of melanoma cells." (PMID 35158973, 2022). "In the SK-MEL-28 melanoma cell line, dabrafenib also showed the highest inhibitory effect on YAP1 compared to the control (Mean Diff." (PMID 35956175, 2022). "In summary, we describe high YAP1/TAZ activity as a molecular driver of MAPKi-resistant MITFlow/AXLhigh melanomas and identify SLC35B2 as a single target for overcoming broad compensatory pathway activation through limiting RTK activity." (PMID 35798875, 2022). "Here, we used BRAFV600E mutant melanoma models with defined YAP1 activity to identify a clinically relevant subgroup of MAPK pathway inhibitor (MAPKi)-resistant melanoma characterized by high YAP1 activity." (PMID 35798875, 2022). "To probe the dependency of MAPKi-resistant MITFlow/AXLhigh melanoma cell lines on YAP1 and TAZ, we generated cell lines with knockout of either YAP1, TAZ, or both." (PMID 35798875, 2022). "In summary, we identify SLC35B2 as a novel vulnerability of YAP1-driven MAPKi resistance in melanoma through limiting heparan sulfation and thereby compensatory RTK activation." (PMID 35798875, 2022). "CTGF, Gyr61, and Birc5 expression levels were reduced, YAP1 phosphorylation was inhibited, and YAP1 was translocated from the cytoplasm to the nucleus in melanoma cells treated with TGF-β1." (PMID 35252214, 2021).
melanoma (continued). "Meanwhile, the functions of LTBP4 overexpression in inhibiting the expression of cleaved caspase-3 and E-cadherin and inhibiting that of Ki67, CTGF, Cyr61 and Birc5 in melanoma cells were abolished by YAP1 overexpression or MST1 overexpression." (PMID 35252214, 2021). "Co-targeting MAPK/PI3K pathway with either integrins, or Src, or YAP1 synergistically inhibited proliferation of melanoma cell lines." (PMID 35006410, 2020). "Consistently, the YAP1 signature has been identified as a driver event of melanoma-acquired resistance." (PMID 32466585, 2020). "For example, lncRNA ATB functioned as a ceRNA to expedite YAP1 through sponging miR-590-5p in malignant melanoma." (PMID 32863773, 2020). "In our study, we found that inhibition of YAP1 or Src sensitized the melanoma cells to MEKi plus PI3K/mTORi." (PMID 35006410, 2020). "A role for TEADs in both melanocytes and melanoma has been previously documented and placing yap1 downstream of Ap2 signalling adds an interesting aspect to Hippo signalling in melanocytes." (PMID 31199790, 2019). "Up-regulation of β-Catenin-LEF1 and concomitant down-regulation of YAP1 have been found to sensitize MAPKi-resistant melanoma." (PMID 29285312, 2017). "This revealed a consistent downregulation of YAP1 mRNA expression both in melanoma cell lines Patient-1-post and Me1007 cells, indicating that the combination of I-BET151 and LBH589 reduces YAP1 expression at the transcriptional level." (PMID 26087189, 2015). "While YAP1 is not frequently mutated in human melanoma, amplifications and mutations of YAP1 have been observed." (PMID 38515849, 2024). "Furthermore, the number of p-AKT-positive (p-AKT+) cells was significantly reduced when YAP1 expression was silenced in CAFs in the melanoma stroma." (PMID 38308096, 2024). "Here, we demonstrated a strong correlation between BRD4 and YAP1 in melanoma patient samples." (PMID 38169595, 2024). "Consistently, YAP1 was enriched in the nucleus after trametinib treatment in melanoma cells, suggesting that increased nuclear YAP1 could lead to resistance to MEK inhibition." (PMID 38169595, 2024). "Together, these results suggest that YAP1 is a main downstream effector of BRD4 in melanoma." (PMID 38169595, 2024). "Interestingly, we observed that melanomas carrying YAP1-overexpressing CAFs (named YAP1) grew more quickly than control tumors carrying wild-type CAFs." (PMID 38308096, 2024). "On the contrary, overexpressing YAP1 in CAFs accelerated melanoma development." (PMID 38308096, 2024). "Next, we addressed the impact of upregulating YAP1 signaling in CAFs on melanoma progression." (PMID 38308096, 2024). "The levels of collagen fibers and fibronectin were significantly reduced in YAP1 KO melanomas." (PMID 38308096, 2024). "We were particularly interested in understanding the genes that were downregulated in shYAP1-GFP/M50, as they may be relevant for identifying the YAP1-mediated mechanism by which CAFs interact with melanoma cells." (PMID 38308096, 2024). "Here, we found that YAP1 expression was significantly increased after trametinib treatment in melanoma patients who did not respond to trametinib and correlated with poor survival of melanoma patients treated with trametinib." (PMID 38169595, 2024). "YAP1 was translocated into the nucleus after trametinib treatment in melanoma cells, which could render resistance to MEK inhibition." (PMID 38169595, 2024). "The purpose of this study was to investigate the mechanism of YAP1 in MEK inhibitor resistance in melanoma and to screen YAP1 inhibitors to further determine whether YAP1 inhibition reverses MEK inhibitor resistance." (PMID 38169595, 2024). "In addition, the mechanism that controls the recycling, internalization, degradation, and expression of N-cadherin in melanoma cells by YAP1 signaling in CAFs needs to be elucidated." (PMID 38308096, 2024).